RNU6-266P (RNA, U6 small nuclear 266, pseudogene)
Gene: Small nuclear RNA gene on chromosome X (22,527,835 to 22,527,941, forward strand). Ensembl gene ENSG00000201095.
Homologues: Orthologues: chimpanzee U6 (98% identical), mouse Gm22583 (89% identical), mouse Gm24921 (89% identical), dog U6 (81% identical). Paralogues in human: RNU6-1060P (93% identical), RNU6-949P (93% identical), RNU6-1024P (91% identical), RNU6-116P (91% identical), RNU6-15P (91% identical), RNU6-19P (91% identical), RNU6-317P (91% identical), RNU6-1011P (90% identical), RNU6-125P (90% identical), RNU6-12P (90% identical), RNU6-13P (90% identical), RNU6-166P (90% identical), and 1290 more.